CCR2 (C-C motif chemokine receptor 2)
Diseases named in the same sentence as CCR2 in open-access papers (continued):
Sharing a sentence is not in itself a finding about the gene and the disease.
liver fibrosis (continued). "There is growing evidence that CCR2/CCR5 and its ligands, including MCP-1 (CCL2) and RANTES (CCL5), are involved in the pathogenesis of liver fibrosis through the promotion of monocyte/macrophage mobilization and tissue infiltration, and the activation of HSCs after liver injury." (PMID 34938271, 2021). "Cenicriviroc is a dual CCR2 and CCR5 antagonist with significant antifibrotic and anti-inflammatory activity in models of fibrosis, such as the mouse peritonitis model, mouse diet-induced NASH model, and rat thioacetamide-induced liver fibrosis model." (PMID 34746195, 2021). "The absence of CCR2 also prevented resolution in models of skin wounds, liver fibrosis, and post-operative ileus." (PMID 33664739, 2020). "Consequently, pharmacological inhibition of monocyte infiltration by blocking CCR2/CCR5 with Cenicriviroc attenuated disease severity as assessed by serum bile acids, histological severity scoring, and liver fibrosis quantification." (PMID 30158929, 2018). "These experiments indicate that interventions to reduce NOX4 or to increase CCR2/CCL2 turnover may attenuate ethanol mediated oxidative stress in HSC at early stages, that later on may result in decreased liver fibrosis." (PMID 28383062, 2017). "Given previous reports on the essential functional role of the MCP-1/CCR2 axis in monocyte recruitment and liver fibrosis, these data indicate that MCP-1 represents one important factor linking RIP3-dependent necroptosis in NASH with liver fibrosis." (PMID 24963148, 2014). "Moreover, adoptively transferred Ly6Chi monocytes traffic into the injured liver and promote fibrosis progression in wildtype and CCR2-/-CCR6-/- mice, which are otherwise protected from hepatic fibrosis." (PMID 23259611, 2012). "The current study showed that Cx3cr1+Ccr2+ Mo-macs expressed the adaptor Myd88 and activated the transcription of S100A4 via CX3CR1/MyD88/NF-κB signaling pathway, resulting in the activation of HSCs and thereby promoting the progression of inflammation and liver fibrosis." (PMID 38627387, 2024). "In the human liver, the expression levels of Fmnl1 and Myh9 in the MMD system (CCR2/CD68/CD11c+ cells in humans) were also increased with collagen deposition, and the expression levels of Fmnl1 and Myh9 increased with aggravation of the liver fibrosis stage (all p<0.05)." (PMID 36911682, 2023). "Therefore, we propose that during the progression of liver fibrosis (especially HBV related), there might be an “amplification loop” between aHSCs and macrophages, and CCL2/CCR2 axis has essential roles in this loop." (PMID 33614685, 2021). "A reduction in hepatic expression of CCR2, eight weeks after a CD11b CD14+ monocyte infusion, may indicate a reduction of Ly6Chi monocytes of pro-inflammatory profile in liver of the animals submitted to cell therapy, favoring the liver fibrosis improvement." (PMID 31015492, 2019). "Several independent studies highlighted the importance of the chemokines receptor CCR2 and its main ligand, MCP-1, for monocyte/macrophage recruitment during experimental hepatic fibrosis, suggesting that inhibition of CCR2 or MCP-1 might bear therapeutic potential in chronic liver diseases." (PMID 28744285, 2017). "Additionally, a C–C chemokine receptor type 2 (CCR2) and type 5 (CCR5) antagonist (cenicriviroc) provided anti-fibrotic activity in adult patients with hepatic fibrosis, but the anti-fibrotic effect did not meet the primary end point in a phase 2 clinical study." (PMID 34035369, 2021).
glioma (90 papers, 2011 to 2025). A benign or malignant brain and spinal cord tumor that arises from glial cells (astrocytes, oligodendrocytes, ependymal cells). "Studies in mice indicate that while a KIAA1549::BRAF fusion is sufficient to generate glioma-like lesions, this is associated with increased Iba1+ microglia infiltration and is inhibited if Ccr2-mediated microglial recruitment is blocked." (PMID 39948623, 2025). "Inoculating a CCR2-deficient strain for glioma model revealed a 30% reduction of TAMs intratumorally." (PMID 35600367, 2022). "We established that bone marrow and glioma-associated CD45high, CD11b+, Ly6Chi/Ly6G- cells co-express CCR2 and CX3CR1." (PMID 36685592, 2022). "We previously established that a glioma-associated CCR2+/CX3CR1+ myeloid cell population also expresses markers consistent with M-MDSCs." (PMID 36685592, 2022). "In a gliomas model, CCR2 deficiency also reduced CD11b+/Ly6Chi/PD-L1+ MDSCs and inhibition of CCR2 increased median survival." (PMID 34804061, 2021). "In comparison, by using the model applied here, only cells of the tumor microenvironment (e.g., myeloid cells, endothelial cells) possess Ccr2-deficiency, while glioma cells still express Ccr2, hence retaining functionality towards CCL2 and other signals." (PMID 32668709, 2020). "Overall, we investigated the impact of Ccr2-deficiency in the glioma microenvironment on tumor progression." (PMID 32668709, 2020). "Using a Ccr2-deficient strain for glioma inoculation revealed a 30% reduction of TAMs intratumorally." (PMID 32668709, 2020). "Collectively, this study proved the critical role of CCR2 in migration to glioma with a result that gliomas in CCL2-deficient mice displayed reduction of both Treg and monocytic MDSCs infiltration." (PMID 31225500, 2019). "The same study also showed that in a mixed BM chimera experiment CCR2-deficient M-MDSCs were defective in glioma accumulation." (PMID 31225500, 2019). "Glioma inoculation using a Ccr2-deficient strain revealed a 30% reduction of TAMs intratumorally." (PMID 36230833, 2022). "Notably, approximately 70% of TAMs infiltrated glioma tissues independently of the CCR2/CCL2 signal which underlines the role of other important recruitment factors." (PMID 32668709, 2020). "In our study of a murine glioma model, the reduced accumulation of TAMs in Ccr2-deficient mice is accompanied by increased tumor volumes based on the enhanced proliferation of glioma cells, changes in their inflammatory gene expression and improved integrity of tumor blood vessels." (PMID 32668709, 2020). "Interestingly, the albumin covered area was reduced in glioma tissues of Ccr2KO animals accompanied by less albumin-stained tumor vessels indicating increased stability and less permeability of blood vessels dependent on Ccr2-deficiency." (PMID 32668709, 2020). "Astrocyte-derived CCL2 can bind CCR2 on glioma cells to maintain stemness characteristics by activating JAK2/STAT3-Notch signaling pathway." (PMID 40243478, 2025). "They investigated the potential of combining CCR2 inhibition with PD-1 blockade to improve treatment outcomes in gliomas resistant to anti-PD-1 therapy." (PMID 40867316, 2025). "Previous studies, including our own, have established the CCR2 pathway as a critical mediator of immunosuppressive myeloid cell trafficking into the glioma microenvironment 16,18,19, 20-26." (PMID 40661379, 2025). "In particular, the CCL2/CCR2 axis has been well documented to mediate Treg recruitment and accumulation across gliomas and diverse types of tumors." (PMID 39034411, 2024). "In this study, we found that bone marrow-derived CCR2+/CX3CR1+ cells adopt an immune suppressive cell phenotype when cultured with glioma-derived factors." (PMID 39272914, 2024). "Targeting the CCL2/CCR2 axis has been shown to reduce tumor infiltrating macrophages in pre-clinical glioma studies." (PMID 38515213, 2024).
glioma (continued). "We determined that bone marrow-derived CCR2+/CX3CR1+ cells adopt an immune suppressive cell phenotype when cultured with glioma-derived factors." (PMID 39272914, 2024). "Our previous work highlighted the presence of a population of myeloid cells in the glioma TME that expresses the chemokine receptors CCR2+ and CX3CR1+." (PMID 39272914, 2024). "C-C chemokine receptor-2 (CCR2) was previously considered as another specific marker to differentiate macrophages in TME, but subsequent studies found that CCR2 is also expressed by microglia, particularly those activated by interaction with glioma cells." (PMID 36969167, 2023). "Previously, it was generally believed that only macrophages expressed CCR2, but now studies have found that microglia in gliomas can also express it." (PMID 37700840, 2023). "The infiltration of peripheral monocytes/brain-intrinsic microglia to the glioma sites is mediated by the interaction between C-C chemokine receptor type 2 (CCR2) expressed on monocytes and C-C motif chemokine ligand 2 (CCL2/MCP-1) expressed by glioma cells." (PMID 37111742, 2023). "In this regard, CCL2 inhibitors or CCR2 antagonists have shown promising results in preclinical models of gliomas, while other subtypes of CC chemokines are still under investigation." (PMID 36980182, 2023). "CCR2+ M-MDSCs represent a prominent infiltrating immune suppressive cell population within murine gliomas." (PMID 36685592, 2022). "This study investigated the T cell suppressive function and chemokine ligand dependency by which CCR2+/CX3CR1+ M-MDSCs traffic into the glioma microenvironment." (PMID 36685592, 2022). "We surprisedly found that C/EBPB co-transcriptionally regulated the level of circ_0012381 and CCR2 in glioma cells." (PMID 36058942, 2022). "KR158B-CCL2 and -CCL7 knockdown murine gliomas contain equivalent percentages of CCR2+/CX3CR1+ MDSCs compared to KR158B gliomas." (PMID 36685592, 2022). "Taken together with our previous data, we posit that this significant difference in survival between low and high expressors is due in part to an elevated level of recruitment of immunosuppressive CCR2+/CX3CR1+ cells into the glioma microenvironment." (PMID 36685592, 2022). "To directly establish if CCR2+/CX3CR1+ cells present within KR158B gliomas are sourced from the bone marrow we generated chimeric mice harboring Ccr2WT/RFP/Cx3cr1WT/GFP bone marrow cells." (PMID 36685592, 2022). "While these previous findings established that CCR2+/CX3CR1+ MDSCs utilize CCR2 to traffic into the glioma microenvironment, it is unclear what chemokines drive this CCR2-dependent migration." (PMID 36685592, 2022). "Conversely, there was a significant reduction (p=0.003) from mean 25.8% to mean 10.8% glioma infiltrating CCR2+/CX3CR1+ cells when comparing KR158B + IgG vs. CCL7 KD + αCCL2 antibody arms." (PMID 36685592, 2022). "To test the concept that CCL2 and CCL7 drive the recruitment of CCR2+/CX3CR1+ cells into the glioma microenvironment, we took a combinatorial targeting approach in vivo." (PMID 36685592, 2022). "In conclusion, we determined that CCR2 and its cognate ligands are prominent regulators of the recruitment of a CCR2+/CX3CR1+ immune suppressive cell to gliomas." (PMID 36685592, 2022). "We have previously reported that three populations of myeloid cells are identified in the glioma microenvironment according to their expression of chemokine receptors CCR2 and CX3CR1." (PMID 36685592, 2022). "CCR2+/CX3CR1+ cells are also reduced within KR158B gliomas upon combination targeting of CCL2 and CCL7." (PMID 36685592, 2022). "KR158B, KR158B CCL2 KD or KR158B CCL7 KD glioma cell lines were implanted in Ccr2+/RFP/Cx3cr1+/GFP mice, and flow cytometry analysis of tumors and bone marrow was conducted 4.5 weeks post-implantation." (PMID 36685592, 2022). "Bone marrow-derived CCR2+/CX3CR1+ cells adopt an immune suppressive cell phenotype when cultured with glioma-derived factors." (PMID 36685592, 2022).
glioma (continued). "A previous study suggested that CCL2/CCR2 plays an important role in the proliferation of glioma cells." (PMID 36058942, 2022). "In CD204−/− glioma, the number of VCAM1+ TAMs and CCR2+ TAM precursor cells was significantly elevated compared to CD204+/+ glioma." (PMID 36686729, 2022). "The lack of effect observed following the implantation of individual CCL2 or CCL7 knockdown gliomas suggested a potential chemokine ligand redundant mechanism utilized by the KR158B cells to recruit CCR2+/CX3CR1+ cells to the TME." (PMID 36685592, 2022). "In combination with the immune checkpoint inhibitor, αPD-1, CCR2 antagonism unmasked an effect of PD-1 blockade in slowing the tumor progression of two immune checkpoint inhibitor-resistant murine gliomas (KR158B and 005 GSC)." (PMID 36685592, 2022). "While these prior studies clearly support targeting CCR2+/CX3CR1+ cells as a means to treat gliomas, a greater appreciation of the immune suppressive and migratory properties of this CCR2+/CX3CR1+ cell population is needed." (PMID 36685592, 2022). "Fittingly, a combination of CCR2 inhibition and anti-PD-1 increased survival of glioma-bearing mice." (PMID 34804061, 2021). "Then, M-MDSCs and PMN-MDSCs migrated to TME in response to MCP-1 and IL-8 released from glioma cells separately, which can recruit monocytes and neutrophils expressing same chemokine receptors, CCR2 or CXCR1/2." (PMID 34211978, 2021). "Monocyte chemotactic protein 1 (MCP-1, CCL2) secreted by glioma cells mediated the recruitment of CCR2+ monocytes and macrophages, and CX3CL1 induced the infiltration of CX3CR+ microglia." (PMID 34211978, 2021). "GAMs produce CCL2, a chemokine recruiting CCR4+ Treg and CCR2+Ly-6C+ monocytic MDSCs in murine gliomas." (PMID 34504786, 2021). "Lacking CCR2 solely on tumor microenvironmental cells leads to enhanced tumor progression, whereby high numbers of GAMs infiltrate gliomas independently of the CCR2/CCL2 signal." (PMID 34071306, 2021). "The CCL2/CCR2 signaling axis is particularly relevant as a therapeutic target since its downregulation inhibits glioma development." (PMID 34359681, 2021). "Even if CCL2 is believed to be the major recruiter of TAMs in gliomas, other factors like CX3CL1, CXCL12, M-CSF and GM-CSF can mobilize TAMs into brain tumor areas, and become relevant under Ccr2-deficiency." (PMID 32668709, 2020). "The higher stability and attenuated leakiness of the tumor vasculature imply improved sustenance of glioma tissue in Ccr2-/- mice." (PMID 32668709, 2020). "CCR2 (C-C Motif Chemokine Receptor 2) is one of the main chemoattractant receptors for macrophages and MDSCs and it has a special relevance in the development of the glioma immune microenvironment." (PMID 32570988, 2020). "Using the syngeneic GL261 glioma model, increased tumor volumes in Ccr2-/- mice were measured, accompanied by reduced infiltration of TAMs and higher integrity of blood vessels." (PMID 32668709, 2020). "The importance of MCP-1 in glioma MDSC recruitment has recently been highlighted, where loss of CCR2, the MCP-1 receptor, demonstrated a reduction of MDSCs in the tumor and bone marrow of glioma bearing mice." (PMID 32625208, 2020). "Knockdown of CCL2 via siRNA inhibited cell proliferation and angiogenesis in the glioma cell line U251 in vitro while overexpression in a U87 glioma cell line increased invasiveness, dependent on presence of CCR2-expressing microglia." (PMID 33282910, 2020). "One study illustrated that glioma-derived CCL2 acts upon CCR2-bearing microglia to produce IL-6, which then stimulates gliomas." (PMID 32194542, 2020). "Still, 70% of IBA1+ cells were recruited into the glioma area independently of the CCR2/CCL2 signal." (PMID 32668709, 2020). "We observed CCR2 expression in TAMs of tumors of the syngeneic GL261 glioma mouse model both on RNA and protein level." (PMID 32668709, 2020). "We found that TAMs of human GBM specimens and of a syngeneic glioma model express CCR2 to varying extents." (PMID 32668709, 2020).
glioma (continued). "This would imply, preferential infiltration of microglia into gliomas of Ccr2-/- mice because these immune cells can migrate independently of CCR2." (PMID 32668709, 2020). "Previously, the function of CCR2/CCL2 signal for glioma biology was investigated by focusing on its ligand CCL2." (PMID 32668709, 2020). "Specifically, the glioma growth is induced by the IL-6 levels, which are produced by microglial cells under stimulation of glioma-released CCL2 that acts upon CCR2 in microglia." (PMID 30123112, 2018). "CCR2+HSCs were markedly superior in enhancing the efficacy of adoptive cellular therapy against glioma relative to bulk unsorted HSCs (p = 0.0005)." (PMID 30333482, 2018). "In glioma-bearing mice, the combination of purified CCR2+HSCs + PD-1 led to significantly increased median survival and long-term survivors over the PD-1 alone group (p = 0.0006), as well as the cohort that received bulk HSCs + PD-1 (p = 0.0233)." (PMID 30333482, 2018). "Next, we found that TAMs in human gliomas were mainly CCR2+/CX3CR1−, indicating that they were monocyte-derived macrophages." (PMID 27602954, 2016). "We immuno-stained the glioma samples and monkey brain sections with an antibody against CCR2 combined with CD3 T-cell marker." (PMID 22319587, 2012). "Immunofluorescence imaging of a checkpoint inhibitor-resistant murine glioma model showed a reduction in CD11b+ myeloid cells when treated with an antagonist of CCR2, a chemokine involved in inflammatory myeloid cell infiltration in the glioma microenvironment." (PMID 39409905, 2024). "We also found that CCR2+/CX3CR1+ M-MDSCs express iNOS in the glioma microenvironment and inhibition of NOS with L-NMMA could recover in vitro proliferation of CD8 T cells, but not CD4 T cell proliferation." (PMID 39272914, 2024). "We first hypothesized that glioma cells induce the differentiation process of CCR2+/CX3CR1+ MDSCs by secreting soluble factors that trigger M-MDSC differentiation." (PMID 39272914, 2024). "Later work comparing steady-state microglia and macrophages revealed that CX3CR1 and CCR2 might be candidate markers to distinguish these cell populations, but these markers proved unreliable in the context of glioma." (PMID 37365324, 2023). "CCL2, referred to as MCP-1 (Monocyte chemotactic protein-1), is secreted by glioma cells and binds to CCR2 expressed on microglia, inducing microglia to recruit to the glioma region and release interleukin-6 (IL-6) thereby promoting the invasion and growth of glioma cells." (PMID 37700840, 2023). "CCR2 inhibition can reduce tumor myeloid cells, suggesting that it may play a role in delaying the progression of gliomas." (PMID 35370869, 2022). "Due to CCR2 expression, Glioma cells are surrounded by microglia." (PMID 36403055, 2022). "Recently, one study reported that combining CCR2 blockade with anti-PD-1 treatment could extend survival in KR158 glioma-bearing mice." (PMID 35920986, 2022). "Using a preclinical glioma model, we demonstrate that CCR2+/CX3CR1+ cells are sourced from the bone marrow, suppress both CD4+ and CD8+ T cells, migrate to CCL2 and/or CCL7 in a CCR2-dependent manner, and are reduced in the glioma microenvironment through combination targeting of CCL2 and CCL7." (PMID 36685592, 2022). "Interestingly, the glioma TME-generated CCL2 mediates the recruitment of inhibitory CCR2+ monocyte MDSCs and Tregs, while mIDH glioma has a reduced CCL2 expression." (PMID 36186781, 2022). "GAMs of human GBM specimens and of a syngeneic glioma model express CCR2 to varying extents." (PMID 34071306, 2021). "A CCR2 antagonist has shown a synergistic effect with an antibody against PD-1, generating a very long-lasting therapeutic effect in preclinical models of murine gliomas." (PMID 32570988, 2020).